TUBA1C (tubulin alpha 1c)
Description:
Tubulin is the major constituent of microtubules, a cylinder consisting of laterally associated linear protofilaments composed of alpha- and beta-tubulin heterodimers. Microtubules grow by the addition of GTP-tubulin dimers to the microtubule end, where a stabilizing cap forms. Below the cap, tubulin dimers are in GDP-bound state, owing to GTPase activity of alpha-tubulin.
Synonyms: TUBA6; MGC14580; MGC10851; bcm948; OZEMA24
Tractability: Small molecule: an approved drug acts on it; a high-quality ligand is known; it belongs to a druggable protein family. PROTAC: ubiquitination databases record sites on it; its protein half-life has been measured; a small molecule that binds it is known. Other modalities: an approved drug acts on it.
Target class: Structural protein
Gene: Protein-coding gene on chromosome 12 (49,188,736 to 49,274,600, forward strand). Ensembl gene ENSG00000167553.
Subcellular location: Cytoplasm, cytoskeleton
Subcellular location (Human Protein Atlas): Microtubules; Primary cilium
Pathways (Reactome):
Cell Cycle: EML4 and NUDC in mitotic spindle formation; Mitotic Prometaphase; Recruitment of NuMA to mitotic centrosomes; Resolution of Sister Chromatid Cohesion; Sealing of the nuclear envelope (NE) by ESCRT-III; Separation of Sister Chromatids; The role of GTSE1 in G2/M progression after G2 checkpoint
Vesicle-mediated transport: COPI-dependent Golgi-to-ER retrograde traffic; COPI-independent Golgi-to-ER retrograde traffic; COPI-mediated anterograde transport; Gap junction assembly; Microtubule-dependent trafficking of connexons from Golgi to the plasma membrane; Translocation of SLC2A4 (GLUT4) to the plasma membrane
Metabolism of proteins: Carboxyterminal post-translational modifications of tubulin; Formation of tubulin folding intermediates by CCT/TriC; Post-chaperonin tubulin folding pathway; Prefoldin mediated transfer of substrate to CCT/TriC
Signal Transduction: Hedgehog 'off' state; RHO GTPases Activate Formins; RHO GTPases activate IQGAPs
Immune System: MHC class II antigen presentation; PKR-mediated signaling
Neuronal System: Activation of AMPK downstream of NMDARs; Assembly and cell surface presentation of NMDA receptors
Organelle biogenesis and maintenance: Cargo trafficking to the periciliary membrane; Intraflagellar transport
Autophagy: Aggrephagy
Cellular responses to stimuli: HSP90 chaperone cycle for steroid hormone receptors (SHR) in the presence of ligand
Developmental Biology: Recycling pathway of L1
Disease: HCMV Early Events
Hemostasis: Kinesins
Gene Ontology:
Molecular function: protein binding; GTP binding; GTPase activity; structural constituent of cytoskeleton; structural molecule activity
Biological process: cell division; cytoskeleton-dependent intracellular transport; microtubule-based process; mitotic cell cycle; neuron differentiation; cytoskeleton organization
Cellular component: cilium; microtubule cytoskeleton; nucleus; vesicle; microtubule; cytoplasmic microtubule; cytoskeleton
Genetic constraint (gnomAD): Loss-of-function variants: 16 observed, 35.31 expected, observed/expected ratio (o/e) 0.45, 90% interval 0.31 to 0.69. The upper end of that interval is the gene's LOEUF score, 0.69, which puts it in group 2 of 6, group 1 being the genes least tolerant of losing a copy. Missense variants: 329 observed, 595.33 expected, observed/expected ratio (o/e) 0.55, 90% interval 0.5 to 0.61. Synonymous variants: 177 observed, 214.18 expected, observed/expected ratio (o/e) 0.83, 90% interval 0.73 to 0.94.
Homologues: Orthologues: macaque TUBA1C (100% identical), chimpanzee TUBA1C (99% identical), mouse Tuba1c (99% identical), rabbit TUBA1C (99% identical), rat Tuba1c (99% identical), tropical clawed frog tuba1c (99% identical), Drosophila melanogaster alphaTub84B (96% identical), Drosophila melanogaster alphaTub84D (96% identical). Paralogues in human: TUBA1A (98% identical), TUBA1B (98% identical), TUBA3C (96% identical), TUBA3D (96% identical), TUBA4A (96% identical), TUBA3E (95% identical), TUBA8 (90% identical), TUBAL3 (73% identical), TUBB4B (43% identical), TUBB4A (43% identical), TUBB (42% identical), TUBB3 (42% identical), and 11 more.
Diseases named in the same sentence as TUBA1C in open-access papers:
TUBA1C is named in the same sentence as 75 diseases in open-access papers, as found by Europe PMC text mining. Sharing a sentence is not in itself a finding about the gene and the disease. The quoted sentences say what the papers report.
glioma (21 papers, 2020 to 2025). A benign or malignant brain and spinal cord tumor that arises from glial cells (astrocytes, oligodendrocytes, ependymal cells). "It has been shown that TUBA1C regulates the cell cycle and is associated with poor prognoses in glioma cells." (PMID 40094001, 2025). "In glioma, TUBA1C has been linked to poor prognosis and its potential oncogenic mechanisms are currently being investigated." (PMID 38891892, 2024). "TUBA1C expression was shown to be substantially expressed in low-grade gliomas and to be an independent risk factor for overall survival." (PMID 38396140, 2024). "In lung adenocarcinoma and low-grade glioma, overexpression of TUBA1C has been associated with a poor prognosis." (PMID 37528357, 2023). "A previous study has shown that high TUBA1C expression is associated with poor prognosis in patients with glioma." (PMID 36185204, 2022). "MYBL2 may promote the proliferation of glioma-associated fibroblasts and TUBA1C had a high expression in M2 macrophages, which confirms and expands on the results of previous studies." (PMID 38577605, 2024). "TUBA1C was mainly expressed in tumor cells and glioma-associated macrophages." (PMID 38577605, 2024). "Furthermore, TUBA1C has been reported to be associated with glioma, and its expression promotes proliferation by regulating the cell cycle and denotes poor prognosis in glioma." (PMID 37091145, 2023). "Among them, high-risk genes MYBL2, C21orf62 and TUBA1C showed higher expression levels in tissues from high-grade gliomas patients (WHO IV grade, GBM), while the expression of low-risk gene KCNIP2 was relatively lower in GBM, which is consistent with our previous hypothesis." (PMID 38577605, 2024). "Moreover, TUBA1C has been reported to be associated with glioma." (PMID 35513790, 2022). "We identified TUBA1B and TUBA1C as the most significant prognostic genes in glioma by integrating results from random forest, univariate, and multivariate Cox regression analyses, highlighting their high weights." (PMID 40094001, 2025). "In summary, these results highlight the potential of TUBA1C as a therapeutic target in glioma treatment strategies." (PMID 39355251, 2024). "Silencing TUBA1C significantly inhibited glioma cell proliferation, migration, and invasion, as well as tumor growth in xenograft models." (PMID 39355251, 2024). "The experimental results showed that the OD value of glioma cells decreased significantly after TUBA1C expression was silenced." (PMID 39355251, 2024). "The findings offer new insights into glioma biology and identify potential therapeutic targets, particularly TUBA1C, aimed at improving patient outcomes." (PMID 39355251, 2024). "Using the Transwell migration and invasion assay, we observed that the invasion and migration ability of glioma cells were significantly reduced after TUBA1C knockdown." (PMID 39355251, 2024). "The results of cell biology assays demonstrated that knockdown of MYBL2 or TUBA1C markedly inhibited the proliferation; and migration of glioma cells." (PMID 38577605, 2024). "Clonogenic assays confirmed that the proliferation ability of glioma cells was weakened after TUBA1C knockdown." (PMID 39355251, 2024). "Knockdown of TUBA1C significantly inhibited glioma cell migration, and invasion in vitro, and reduced tumor growth in vivo." (PMID 39355251, 2024). "To investigate the key role of TUBA1C in the pathogenesis of glioma, we selected the LN299 and U87 glioma cell lines as research subjects and used targeted siRNA-mediated knockdown technology to regulate the expression of TUBA1C." (PMID 39355251, 2024). "Taken together, we have revealed the key role of TUBA1C in promoting the proliferation, migration, and invasion of glioma cells." (PMID 39355251, 2024). "To further investigate the impact of TUBA1C suppression on the migration and invasion ability of glioma cells, we conducted in-depth analyses." (PMID 39355251, 2024).
glioma (continued). "In recurrent glioma, the probability of survival was higher in the TUBA1C low expression group in all WHO grades (p < 0.0001) and the WHO grade III (p = 0.012) subclassification." (PMID 35513790, 2022). "We further investigated the expression of TUBA1C in gliomas and its impact on the prognosis of patients with gliomas." (PMID 35513790, 2022). "Tuba1c is an α-tubulin subtype known to be highly expressed in glioma brains and is related to immune cell infiltration in the brain, and cell mitosis and division." (PMID 36614117, 2022). "Our study showed that TUBA1C was highly expressed in glioma types with high malignancy and in recurrent gliomas." (PMID 35513790, 2022). "Immunohistochemical analysis also confirmed that TUBA1C expression was higher in high-grade gliomas than in low-grade gliomas." (PMID 35513790, 2022). "In a recent study, TUBA1C expression was reported to be significantly higher in gliomas than in normal brain tissue, indicating a poorer prognosis." (PMID 36474171, 2022). "One study indicates that tubulin alpha-1C chain (TUBA1C) may potentially regulate the pathogenesis of glioma through Janus kinase (JAK)/signal transducer and activator of transcription (STAT) (JAK-STAT) pathway." (PMID 40475540, 2025). "The roles of MYBL2 and TUBA1C on tumor progression were investigated in glioma cells." (PMID 38577605, 2024). "Overall, MYBL2 and TUBA1C promoted proliferation and migration, which may play an important role on glioma progression." (PMID 38577605, 2024). "We evaluated the impact of TUBA1C knockdown on the viability of glioma cells using the CCK-8 assay." (PMID 39355251, 2024). "Our findings further revealed that TUBA1C knockdown significantly inhibited the malignant biological behaviors of glioma cells, demonstrating that TUBA1C is a promising target for the treatment of glioma." (PMID 39355251, 2024). "In this study, we found that MYBL2 and TUBA1C, highly expressed in high-grade gliomas, may be involved in the process of PANoptosis and promoted the proliferation and migration of glioma cells." (PMID 38577605, 2024). "This discovery underscores the importance of TUBA1C as a potential therapeutic target in glioma treatment and may provide new ideas and methods for future glioma treatment." (PMID 39355251, 2024). "The biological significance of two panoptosis-related predictors, MYB proto-oncogene like 2 (MYBL2) and tubulin alpha-1C chain (TUBA1C), was also confirmed by the experimental knockdown of both predictors, which resulted in a significant inhibition of glioma cell proliferation and migration." (PMID 39062119, 2024). "Notably, knockdown of TUBA1C suppressed proliferation and migration, along with the induction of apoptosis and G2/M phase arrest in glioma cells." (PMID 38171932, 2023). "Furthermore, TUBA1C demonstrates up-regulation in glioma tissues in comparison to normal brain tissues." (PMID 38171932, 2023). "There is clear evidence that PTX3, TIMP1, and TUBA1C are related to glioma invasion." (PMID 37091145, 2023). "TUBA1C inhibition reduced glioma cell proliferation through cell cycle arrest." (PMID 36185204, 2022). "Given that TUBA1C affects the cell cycle and regulates tumour-infiltrating cells in the tumour microenvironment, its knockdown can suppress the migration of U87and U251 cells (human glioma cells) and induce apoptosis in vitro." (PMID 36466547, 2022). "Overall, TUBA1C expression increased in gliomas as WHO classification increased." (PMID 35513790, 2022). "In primary gliomas, the probability of survival was higher in the TUBA1C low expression group than in the TUBA1C high expression group in all WHO grades (p < 0.0001) and in the WHO grade II (p = 0.032), WHO grade III (p = 0.032) and WHO grade IV (p = 0.017) subclassifications." (PMID 35513790, 2022). "In addition, TUBA1C is associated with a poor prognosis in HCC, glioma, and lung adenocarcinoma, which is consistent with the results of the present study." (PMID 36466547, 2022).
glioma (continued). "In addition, knockdown of TUBA1C also inhibited proliferation and migration of glioma cells, leading to apoptosis and G2/M phase arrest." (PMID 36474171, 2022). "Besides, we also confirmed the biological functions of two oncogenic predictors (MYBL2 and TUBA1C) by cell experiments, which revealed that knockdown of MYBL2 or TUBA1C could significantly inhibit the proliferation and migration of glioma cells." (PMID 38577605, 2024). "Moreover, we validated the expression and role of TUBA1C in gliomas." (PMID 35513790, 2022). "While TUBA1C and FBXO17 have been extensively studied in glioma and are known to promote tumor progression, TOM1L1's role in glioma remains underexplored, particularly in the context of PTM‐mediated mechanisms." (PMID 40090864, 2025). "Moreover, functional experiments were performed to evaluate the roles of risk genes in the cell viability and cell number of glioma U87 and U251 cells, which demonstrated that silencing BGN, SDC1, SERPINA1, TUBA1C, C1GALT1C1L and SPTBN5 could inhibit the growth and viability of glioma cells." (PMID 38396140, 2024). "Immunohistochemical analysis showed that TUBA1C expression was highest in glioblastoma (GBM) tissues, second highest in low-grade glioma (LGG) tissues and lowest in normal tissues." (PMID 35513790, 2022). "Recently, it was demonstrated that glioma tissues have higher TubA1C expression than normal brain tissues and that high TubA1C levels are an indicator of worse prognoses in glioma patients, thereby suggesting that TubA1C may be a therapeutic biomarker for gliomas." (PMID 35008169, 2021). "Due to heterogeneity of glioma, we additionally investigated the patient prognosis with CDK4/CDK6 and TUBA1C expression in every grade of glioma in CGGA datasets." (PMID 32860670, 2020). "Four PANoptosis-related predictors (MYBL2, TUBA1C, C21orf62 and KCNIP2) were identified and predictive PANRG score model was developed for glioma based on bulk-seq and scRNA-seq analysis, which is significantly associated with tumor immune landscape and therapeutic responses." (PMID 38577605, 2024). "In addition, TUBA1C expression was highest in WHO IV gliomas, intermediate in WHO III gliomas and lowest in WHO II gliomas." (PMID 35513790, 2022). "Furthermore, TUBA1C is involved in the migration and proliferation of hepatocellular carcinoma (HCC) and performs a crucial function in the development of glioma and lung cancer." (PMID 36466547, 2022). "In addition, TUBA1C, SBF2-AS1, and SMYD2 have similar expression and prognostic impact in glioma." (PMID 38552216, 2024). "Recent studies have demonstrated that TUBA1C is an important mediator of cell cycle signaling, and it is aberrantly expressed in several malignancies, such as lung adenocarcinoma (LUAD), mammary cancer, and low-grade glioma and is also involved in the growth, migration, and invasion of tumor cells." (PMID 36941595, 2023). "Finally, functional experiments were performed to evaluate the roles of risk genes in the cell viability of glioma cells, which demonstrated that silencing BGN, SDC1, SERPINA1, TUBA1C, C1GALT1C1L and SPTBN5 could inhibit the growth and viability of glioma cells." (PMID 38396140, 2024). "Results showed that patients with higher TUBA1C expression had shorter survival rates than those of the counterparts in grades II, III and IV primary glioma and grade III recurrent glioma, but not in grades II and IV recurrent glioma." (PMID 32860670, 2020).
breast carcinoma (13 papers, 2019 to 2025). "In summary, high messenger RNA (mRNA) expression of TUBA1C is an independent risk factor for poor prognosis of breast cancer." (PMID 38032902, 2023). "Univariate and multivariate Cox analyses also showed that high TUBA1C expression was an independent risk factor for OS in breast cancer patients." (PMID 38032902, 2023). "Furthermore, a prior study indicated that TUBA1C was statistically associated with the expression of RP11-480I12.5 in breast cancer (BRCA) and demonstrated prognostic significance." (PMID 39355251, 2024). "In addition, univariate and multivariate Cox analyses also showed that high TUBA1C expression was an independent risk factor for OS in breast cancer patients (hazard ratio [HR] = 1.5430, 95% confidence interval [CI]: 1.1927–1.9962, P = 0.0010)." (PMID 38032902, 2023). "In addition, a previous study claimed that TUBA1C was statistically linked to the expression of RP11-480I12.5 in breast cancer (BRCA) and had prognostic value." (PMID 35513790, 2022). "Recent studies have demonstrated that TUBA1C is upregulated in different types of cancers, including bladder cancer, breast cancer, and pancreatic ductal adenocarcinoma, and this upregulation is correlated with increased tumor progression and metastasis." (PMID 39301023, 2024). "In summary, a comprehensive bioinformatics analysis using the TCGA database was performed, and the results showed that TUBA1C is a potential biomarker that predicts a poor prognosis in breast cancer." (PMID 38032902, 2023). "In this study, the expression and potential prognostic value of TUBA1C in breast cancer were investigated." (PMID 38032902, 2023). "Univariate and multivariate analyses (Cox regression analyses) confirmed that TUBA1C was an independent prognostic factor for the OS of breast cancer patients." (PMID 38032902, 2023). "By downloading RNA-seq data from the TCGA database, differences in TUBA1C expression between breast cancer and normal breast tissues were statistically analyzed." (PMID 38032902, 2023). "Analysis of the HPA database showed that the upregulation of TUBA1C expression in lung cancer, liver cancer, pancreatic cancer, and breast cancer tissues exhibited the same trend." (PMID 38032902, 2023). "In this study, the gene expression profile of TUBA1C in The Cancer Genome Atlas (TCGA) was extracted for analysis, and the prognostic value of TUBA1C in breast cancer was comprehensively evaluated." (PMID 38032902, 2023). "The effect of TUBA1C expression on the survival of breast cancer patients was assessed by Kaplan-Meier curve, Cox regression analysis, and the Kaplan-Meier plotter (an online database)." (PMID 38032902, 2023). "The results confirmed that high TUBA1C expression in breast cancer was closely correlated with survival time, survival status, and tumor size." (PMID 38032902, 2023). "The results showed that compared with normal breast tissue, TUBA1C expression was significantly increased in breast cancer tissues (P = 2.558e-51)." (PMID 38032902, 2023). "The Kaplan-Meier curve showed that the OS of breast cancer patients with high TUBA1C expression was lower than that of patients with low TUBA1C expression (P < 0.05)." (PMID 38032902, 2023). "Correlation between expression of TUBA1C and clinicopathological features of patients with breast cancer (logistic regression)." (PMID 38032902, 2023). "The Wilcoxon signed-rank test, Kruskal-Wallis test, and logistic regression analysis were performed to confirm the correlations between TUBA1C expression and the clinical characteristics of breast cancer patients." (PMID 38032902, 2023). "It has been revealed that high the expression of TUBA1C predicts a poor prognosis of hepatocellular carcinoma, lung adenocarcinoma, breast cancer, and osteosarcomas." (PMID 34721547, 2021). "TUBA1C can be used as a potential oncogene and prognostic molecular marker in breast cancer." (PMID 40433461, 2025).